IL7 (interleukin 7)
Diseases named in the same sentence as IL7 in open-access papers (continued):
Sharing a sentence is not in itself a finding about the gene and the disease.
HIV-1 infection (continued). "In our experiments, although the magnitude of HIV-1 enhancement was proportional to the length of exposure to IL-7, we found that IL-7 does not need to be present during the entire culture period to up-regulate HIV-1 infection." (PMID 23408885, 2013). "Although IL-7 can enhance HIV-1 infection of T cells, infection of resting memory T cells mediated by cell-to-cell spread does not require IL-7; furthermore, IL-7 increased CD69 expression on infected cells even when added 48 h post-infection." (PMID 35417711, 2022). "These include one round HIV-1 infection, latently infected Jurkat (lymphoblastoid T cells), THP (monocytes) cell lines, chronically infected CEM T cells (ACH-2) and primary CD4+ T cells within the pool of infected PBMCs treated with IL-7 to transfer them to quiescent phase." (PMID 26178009, 2015). "Interestingly, while HIV-1 infection alone induced upregulation of CD69, additional exposure of these HIV-1-infected resting memory T cells to the homeostatic T cell cytokine interleukin-7 (IL-7) further boosted CD69 upregulation 4-fold, compared with HIV-1 or IL-7 alone." (PMID 35417711, 2022). "One possibility is that while HIV-1 infection impairs CD4+ T cell memory formation, this is incompletely abrogated and a small number of cells infected early in untreated infection may become long-lived memory CD4+ T cells despite profound dysregulation in IL-7 signaling at the population level." (PMID 31507594, 2019). "IL-15, but not IL-7, improved the survival of CCR5+CD4+ T cells, drove their expansion, and facilitated HIV-1 infection in vitro and in humanized mice." (PMID 36821374, 2023). "IL-7 and IL-2 were previously used to increase CD4+ T cell counts in HIV-1 infection, however, no improvement in their function were reported." (PMID 33384690, 2020).
Immunodeficiency (34 papers, 2005 to 2026). Failure of the immune system to protect the body adequately from infection, due to the absence or insufficiency of some component process or substance. "According to previous studies, the loss of IL-7 and IL-7R can lead to severe immune deficiency, and IL-7R acts a vital role in the generation and long-term maintenance of memory CD8+ T cells." (PMID 38748299, 2024). "The IL-7/IL-7R pathway is essential for lymphocyte development and disturbances in the pathway can lead to immune deficiency or T cell mediated destruction." (PMID 31024566, 2019). "Recently, adjuvant recombinant human IL-7 (rhIL-7) was demonstrated to be effective in sustaining CD4+ recovery in HIV-positive patients with different degrees of immune deficiency." (PMID 21209878, 2010). "IL-7 is a cytokine that supports host defence by regulating the homeostasis of the cells of the immune system such that congenital deficiency of IL-7 leads to severe immunodeficiency." (PMID 39946431, 2025). "Understanding of this interaction can have therapeutic potential for the design of new immunomodulatory strategies, especially in chronic disease or immune deficiency patients, for whom the homeostasis between IL-2 and IL-7 might be compromised." (PMID 41305439, 2025). "Thus, as seen in our patients with WHIM syndrome, SYKgaln-of-function, and combined immunodeficiency due to IL-7 deficiency, we strongly suggest undergoing genetic testing in all patients diagnosed with common variable immunodeficiency." (PMID 39836844, 2024). "The fundamental role of IL-7 has been demonstrated in both humans and in mice with deficiency in either IL-7 or the IL-7 receptor (IL-7R) resulting in impaired thymic development of mature lymphocytes resembling severe combined immune deficiency." (PMID 30842774, 2019). "Since γc is shared by receptors for IL-4, IL-7, IL-9, IL-15, and IL-21 and a loss of γc function causes immunodeficiencies in both humans and mice, it is anticipated that knockdown of γc may lead to severe systemic side effects." (PMID 24223832, 2013). "In this context, IL-7 appears to bridge muscle and immune health, potentially mitigating both sarcopenia and immune dysfunction through exercise-mediated pathways." (PMID 41441428, 2025). "We highlight the cases of WHIM syndrome (warts, hypogammaglobulinemia, immunodeficiency, and myelokathexis), SYTC gain-of-function, APDS2, SAVI, and IL-7 deficiency." (PMID 39836844, 2024). "Jak3 knockout mouse model showing Il-2, Il-4, Il-7, Il-9, and Il-15 conduction defects, elevated levels of Il-6 and Il-17a and severe immunodeficiency, defects in barrier function lead to Ulcerative colitis (UC)." (PMID 33777833, 2021). "Therapeutic uses for treatment of immunodeficiency and cancer of IL-7/anti-IL-7 antibody complexes have been discussed." (PMID 26870966, 2016). "Collectively, these results suggest that our IL-7 reporter system can be utilized in large-scale chemical library screening to reveal novel IL-7 regulatory pathways and to identify potential drugs for development of new treatments in immunodeficiency disease." (PMID 27589392, 2016). "Both immune deficiencies and autoimmune manifestations have been reported in ICL, which appears consistent with an impairment of both IL-7 and IL-2 systems." (PMID 23383227, 2013). "Previous studies associated IL-7 with pain in patients with cancer and also with myalgic encephalomyelitis, which has main symptoms similar to those of TMD patients such as fatigue, immune dysfunction, and musculoskeletal pain." (PMID 40142185, 2025). "Given that IL-7 plays a role in the immune system, the diabetes chronic wound may involve immune dysfunction." (PMID 37217704, 2023). "Therefore, modulation of IL-2/IL-2R and IL-7/IL-7R signaling with biological therapies has great potential as countermeasures to restore immune dysfunction of crew members." (PMID 37624890, 2023).
Immunodeficiency (continued). "In fact, lack of IL-7 is associated with severe immunodeficiency and presence of IL-7 in blood cancer patients is an indication of better prognosis which is associated with activating immune effector cells in tumor hosts." (PMID 29246138, 2017). "IL-7 is crucial for thymic T cell development and peripheral maintenance, while a defective IL-7 receptor presents as T-cell–deficient (but not NK-cell–deficient) severe combined immunodeficiency." (PMID 39403378, 2024). "The upregulation of genes such as IL‐7 and CD8 suggests the organism's sustained efforts to drive hematopoietic stem cell (HSC) differentiation into lymphocytes, implying a potential immunodeficiency in TK9‐MRD mice." (PMID 41144740, 2026). "Increased levels of IL-7 leads to T cell activation and lack of IL-7 leads to severe immunodeficiency." (PMID 27401917, 2016). "In summary, we demonstrated that HIV infection alters IL-7 activity in thymocytes independent of CD127 expression suggesting a potential mechanism by which HIV infection interrupts thymic output and contributes to immune deficiency." (PMID 21920046, 2011). "Importantly, no mutations were detected in other known EV-associated or immunodeficiency-related genes, such as RHOH, IL7, CORO1A, STK4, DOCK8, or CARMIL2, supporting the notion that the identified TMC6 and TMC8 variants may represent the primary genetic contributors in this case." (PMID 40534698, 2025).
leukemia (34 papers, 2006 to 2024). A malignant (clonal) hematologic disorder, involving hematopoietic stem cells and characterized by the presence of primitive or atypical myeloid or lymphoid cells in the bone marrow and the blood. "Aberrations in the IL-7/IL-7R/JAK/STAT signaling pathway have also been associated with leukemia, with particular bad prognosis in adult patients with T-ALL." (PMID 34276694, 2021). "Moreover, in vivo experiments exhibited that the consumption of IL-7 contributes to the development of T-ALL, while IL-7 deficiency reduced the proliferation of leukemia cells." (PMID 36389666, 2022). "A study on B-ALL patients discovered that the expression levels of cytokines IL-7, IL-10 and IL-15 and their receptors were higher than those in healthy controls, suggesting the existence of a complex autocrine/paracrine mechanism underlying the regulation of leukemia cell functions." (PMID 28408741, 2017). "The role of IL-7 in the expansion and acceleration of leukemia progression has been revealed by engrafting T-ALL cell lines and primary T-ALL samples in immunocompromised mouse models after IL7 KO." (PMID 38571491, 2024). "This switch in growth factor dependency was confirmed in vivo, where the acquired IL-7-independence of leukemia cells was sufficient to sustain the expansion of leukemic blasts in NSG recipients treated with IL-7R-blocking antibody." (PMID 38519798, 2024). "Many studies on hematologic diseases prove that the IL7/IL7R axis is also an important factor in the development of leukemia." (PMID 37381714, 2023). "The DNA‐binding function and kinase activity of Pax5‐Jak2 as well as IL‐7 signaling contributed to leukemia development." (PMID 35156727, 2022). "In agreement with this, DNM2 mutations co-occur with additional activating alterations in the IL-7 signaling pathway, suggesting a cooperation between these genetic alterations in leukemia development." (PMID 34066732, 2021). "IL-7 is known to induce the differentiation and development of haematological malignancies, such as lymphomas and leukaemias." (PMID 34575268, 2021). "To corroborate these findings, we next evaluated the impact of CIGB-300 on the T-ALL primary leukemia-like IL-7-dependent cell line TAIL7." (PMID 32471246, 2020). "Increased secretion of cytokines, including IL-7 and IL-3, promotes the survival and proliferation of leukemia cells through the activation of the phosphatidylinositol 3-kinase (PI3K) and mitogen-activated protein kinase (MAPK) pathways." (PMID 33105727, 2020). "Using CX-4945, we demonstrated that CK2 pharmacological inhibition impaired JAK/STAT5 and PI3K/Akt signaling pathway activation triggered by IL-7 or by IL7R mutational activation and consequently impaired the pro-leukemia effects of IL-7." (PMID 32471246, 2020). "B12 is able to inhibit IL-7-dependent and mutant-dependent IL-7R-mediated signaling and induce leukemia cell death." (PMID 32849527, 2020). "We also revealed the existence of a crosstalk between CK2 activity and the signaling mediated by interleukin 7 (IL-7), a critical leukemia-supportive cytokine." (PMID 32471246, 2020). "IL-7 cytokine, as one of the important growth factors produced by bone marrow and thymic stroma, functions as a powerful proliferative stimulus for leukemia cells." (PMID 31592121, 2019). "IL-7 is a critical cytokine for the development of T and B cells that, in excess, allows the development of leukaemia in both mice and humans." (PMID 24551160, 2014). "Similarly, CXCR4 blocking also prevents leukemia-induced IL7 downregulation and inhibits leukemia growth." (PMID 36912771, 2023). "Therefore, it is unpracticable to apply IL-7, a cytokine that contributes to leukemia development, as an adjuvant for cancer vaccines against hematopoietic malignancy for safety considerations." (PMID 36389666, 2022). "Similarly, IL-7-mediated signaling contributes to leukemia development and cancer cells typically have increased production of proteases such as MMP-9 and other MMPs." (PMID 34276694, 2021).
leukemia (continued). "In these models, IL-7 deficiency resulted in a decreased expansion of T-ALL cells in the bone marrow, reduced infiltration in the peripheral blood and extramedullary sites and delayed leukemia-associated death." (PMID 34066732, 2021). "Like normal T and B progenitors, most T-ALL and B-ALL cells express functional receptors for IL-7 (IL-7R) which are able to promote leukemia survival and proliferation both in vitro and in patient- derived xenograft assays, suggesting a role for IL-7R/IL-7 pathway in ALL progression." (PMID 34026651, 2021). "In summary, the role of cytokines in leukemia cell survival and proliferation makes IL-3 and IL-7 potential therapeutic targets for obesity-driven B-cell ALL, while IL-7 alone may be a target for obesity-driven T-cell ALL." (PMID 33105727, 2020). "Moreover, these mAb chimeras inhibit IL-7R signaling at low IL-7 concentrations, mediate antibody-dependent cell mediated cytotoxicity in vitro and are effective in controlling established and relapsing leukemia in vivo." (PMID 32849527, 2020). "Moreover, there is evidence for a crosstalk between CK2 and JAK/STAT signaling pathway that can contribute to leukemia cell survival and proliferation, including in response to critical microenvironmental stimuli, such as interleukin-7 (IL-7)." (PMID 32471246, 2020). "In summary, we demonstrate that the clinical-grade cell-penetrating peptide CIGB-300 is able to block proliferation and induce cell death of both cell lines and primary T-ALL patient cells, even in the presence of leukemia-supportive signals such as IL-7 or stromal cell co-culture." (PMID 32471246, 2020). "Ultimately, the cooperative effect of Notch and IL-7 may have a critical role in leading to uncontrolled proliferation and leukemia transformation." (PMID 31772299, 2020). "Moreover, studies in vitro showed that leukemia blasts from a majority of the patients (~ 70%) display IL-7R and that IL-7 promotes their survival and proliferation." (PMID 30850736, 2019). "IL-7 stimulates the progression of some types of lymphomas and leukaemias and in non-small cell lung cancer, it was reported that IL-7 targeted gene therapy may be effective in modifying host anti-tumor responses." (PMID 17205128, 2006). "Ph+ ALL cells that survive treatment with BCR-ABL inhibitors in microenvironments containing IL7 may act as leukemia initiating cells and disseminate to other locations when inhibitor concentrations decline or when inhibitor resistance is induced by somatic mutations." (PMID 32581241, 2020). "T cells expressing a CAR containing a distal IL7Rα domain (CD28.IL7R.ζ) had superior leukemia control in vivo when compared with the T cells expressing a CAR with a proximal IL7Rα domain (IL7R.CD28.ζ) and with CAR-T cells secreting IL7." (PMID 39186002, 2024). "The fourth-generation CAR-T cells, engineered to secrete IL7 and IL15, demonstrated high anti-leukemia activity in preclinical animal models." (PMID 38927401, 2024). "IL-7 and IL-7R activate three main signaling networks: STAT5, PI3K/AKT/mTOR and MEK/ERK, leading to leukemia cell progression and survival, also with regard to T-ALL." (PMID 34026651, 2021). "In the murine bone marrow, IL-3 and IL-7 promote B-cell proliferation and survival and CXCL12 is essential for expanding leukemia cells." (PMID 33105727, 2020). "Taking into consideration the role of IL-7 in promoting T-ALL cell survival and proliferation in vitro and T-ALL expansion in vivo, we also determined the ability of CIGB-300 to target leukemia cells in the presence of IL-7." (PMID 32471246, 2020). "Moreover, CIGB-300 overcomes IL-7-mediated T-ALL cell growth and viability, while preventing the positive effects of OP9-delta-like 1 (DL1) stromal support on leukemia cells." (PMID 32471246, 2020). "Consistently, tumor Pax5-het/Aid-het and Pax5-het/Aid-KO pro-B cells grow independent of IL7 and can initiate leukemia in secondary transplant recipients." (PMID 31804490, 2019).
leukemia (continued). "Cytokines activating STAT5 additionally such as IL-2, IL-3, IL-7, GM-CSF and many others could enhance the effect of BCR-ABL and promote leukemia induction and maintenance." (PMID 28753604, 2017).
prostate carcinoma (34 papers, 2006 to 2026). A carcinoma that arises from epithelial cells of the prostate gland. "Previous studies depict that high levels of IL-7 and IL-7R expression is associated with lymph node metastasis, poor survival, and poor prognosis in breast, lung, and prostate cancers." (PMID 38424167, 2024). "The gene expression profile of human prostate cancer cells from The Cancer Genome Atlas revealed that EMT pathways are strongly associated with prostate cancers that highly express both IL-7 and IL-7Rα." (PMID 31061414, 2019). "It has been reported that elevated IL-7 expression in prostate cancer is associated with poor prognosis." (PMID 28486560, 2017). "In prostate cancer, high IL-7 expression correlates with poor prognosis because IL-7R activation promotes invasion and migration via the AKT/NF-κB pathway and matrix metalloproteinase (MMP) regulation." (PMID 41596598, 2026). "In primary prostate cancer, the immune microenvironment is characterized by suppressive myeloid cells and exhausted T cells, and the expression level of IL-7/IL-7R in this microenvironment is significantly higher than that in normal tissues." (PMID 41360767, 2025). "Building on the previous success in utilizing interleukin-7 (IL-7) co-expression to enhance CAR-T cell therapy efficacy in a prostate cancer model, the present study presents a significant step forward." (PMID 39450160, 2024). "The results from a preclinical study showed that the combination of IL-7 and sip-T significantly inhibited tumour growth in a mouse model of prostate cancer, with potential clinical efficacy that should be further evaluated in clinical trials." (PMID 38675377, 2024). "Previous studies have shown that the IL-7/IL-7 receptor axis stimulates the invasion and migration of prostate cancer cells via the AKT/NF-kB pathway." (PMID 37910571, 2023). "Elevated IL-7 in prostate cancer patients with early stage also promotes the invasiveness of prostate cancer cells by inducing epithelial–mesenchymal transition." (PMID 34575268, 2021). "The level of IL-7 expression has been suggested as impacting the rate of survival of patients with prostate cancer, and upregulated expression of both IL-7 and its receptor, IL-7R, have been detected in prostate tumor cells." (PMID 32585812, 2020). "Inhibition of the IL-7/IL-7R axis decreases prostate cancer cell invasion, migration, as well as MMP3 and MMP7 expression via suppressive effects on both the AKT and NFκB pathways." (PMID 32585812, 2020). "In this study, we utilized NKG2D-based CAR to treat prostate cancer, and improved the therapeutic effect by co-expression of IL-7." (PMID 32698361, 2020). "IL-7 directly enhances the migration and invasion of PC-3 cells; thus, we explored the potential of IL-7 as a target for the inhibition of prostate cancer metastasis." (PMID 31061414, 2019). "A study has recently reported that IL-7 contributes significantly to the invasion and migration of prostate cancer cells." (PMID 31915416, 2019). "But in a solid tumor, the IL-7/IL-7R axis promoted prostate cancer cell invasion and migration by activating the AKT/NF-κB pathway and increasing MMP-3 and MMP-7 expression." (PMID 31915416, 2019). "In this study, we modulated the expression of IL-7Rα and used inhibitors to show that IL-7 directly increases the migration and invasion of prostate cancer cells and assessed the potential of IL-7 and IL-7Rα as targets for anticancer drugs." (PMID 31061414, 2019). "We then validated the mechanism of IL-7-induced tumor cell migration and invasion in prostate cancer using The Cancer Genome Atlas (TCGA) database." (PMID 31061414, 2019). "Taken together, these results showed that IL-7 acts on prostate cancer cells expressing IL-7Rα to increase their migration and invasion." (PMID 31061414, 2019). "Elevated expression of IL‐7 and IL‐15 in prostate tissues and its increased serum level was confirmed in patients with early‐stage prostate cancer." (PMID 26880719, 2016).